CX3CR1 (C-X3-C motif chemokine receptor 1)
Diseases named in the same sentence as CX3CR1 in open-access papers (continued):
Sharing a sentence is not in itself a finding about the gene and the disease.
infection (continued). "Second, it mediates binding to CX3CR1 in primary human airway epithelial cells in vitro as the first step in the infection of cells, and the anti-G antibody effectively neutralizes RSV in these cells." (PMID 34372490, 2021). "FKN is involved in the recruitment of monocytes to the site of infection and binds to its receptor CX3CR1 expressed by macrophages." (PMID 33540888, 2021). "The G glycoprotein utilizes heparan sulfate proteoglycans (HSPGs) on the surface of immortalized cells and likely utilizes CX3CR1 on HBE to initiate infection." (PMID 33831114, 2021). "In our model, microglia downregulated CX3CR1 over the course of infection, while Ly6Chi macrophages expressed CX3CR1, with varied CCR2 expression." (PMID 34311763, 2021). "TEM cell populations expressing PD-1, CD44, and CD11a and either CD27hi (Sp cluster 2) or CX3CR1 (Sp cluster 4) were dominantly present in LCMV clone 13 infection." (PMID 33458613, 2021). "First, G plays an important role in the first step of infection, binding to cell surface molecules through GAGs and/or CX3CR1." (PMID 34372490, 2021). "These conclusions followed from differences in responses to infection with a virus with an intact or inactivated CX3C motif or the co-administration of anti-CX3CR1 antibodies." (PMID 34372490, 2021). "In contrast, infection with an MPT70-overexpressing Mtb strain promoted highly differentiated KLRG1+CX3CR1+ CD4 T cells with limited lung-homing capacity." (PMID 33879592, 2021). "This chemokine receptor is expressed on the apical surface of ciliated cells in HBE cultures and infection can be partially inhibited by monoclonal antibodies to CX3CR1." (PMID 33831114, 2021). "A TEM cell cluster in the spleen expressing Ly6C, CD27, CXCR3, and CD127 (Sp cluster 12) was more abundant in LCMV Armstrong, whereas a KLRG1+CX3CR1+ subset was more related to MCMV-GP33 infection." (PMID 33458613, 2021). "CD86 was higher expressed on hepatic classical monocytes from testosterone-treaded mice upon infection, whereas the expression of CX3CR1 was only slightly reduced compared to the control group." (PMID 32651360, 2020). "Infection only modestly reduced CX3CR1 in WT CD45loCD11b+ microglia but the overall peak MFI was not altered." (PMID 33253295, 2020). "Results from this study indicates that infection induced by B. anthracis spores significantly increases long-duration (> 30 min) contact between macrophages and CX3CR1-DCs." (PMID 33520993, 2020). "Together, the greater abundance of ITGAL, CD44, and CX3CR1 after calving suggested a potential greater influx and adhesion of leukocytes into tissues, likely contributing to decrease the incidence of infection postpartum." (PMID 32260288, 2020). "Susceptibility to secondary infection was thus inversely proportional to the extent of Mo expansion observed in CCR2- and CX3CR1-deficient mice, suggesting a protective role of Mo in these infectious conditions." (PMID 32425929, 2020). "G binding to CX3CR1 also mediates infection of primary human airway epithelial cells and CX3CR1 is considered an RSV receptor in these cells." (PMID 32824936, 2020). "Surprisingly, microglial CX3CR1 expression was significantly lower in Ifit2-/- compared to WT mice following infection, although levels were similar in naïve mice." (PMID 33253295, 2020). "Here, we investigated the role of CX3CR1 in the neuroinflammation induced by infection with Japanese encephalitis virus (JEV), a neurotrophic virus." (PMID 31316515, 2019). "CX3CR1 played an important role in the rapid delivery of JEV Ags in dLNs from the peripheral site of infection at an early stage after peripheral JEV inoculation." (PMID 31316515, 2019). "CX3CR1 and interleukin-6 (IL-6) are both involved in inducing inflammation in response to infection and tissue injuries, while IL-6 is also involved in native T-cell differentiation." (PMID 31608121, 2019).
infection (continued). "The surface of the virion is decorated with the fusion glycoprotein (RSV F) and the attachment glycoprotein (RSV G), which binds to CX3CR1 on human airway epithelial cells to mediate viral attachment and subsequent infection." (PMID 29509814, 2018). "In contrast, heparan sulfate is not detectable on the surface of human airway epithelial cells and infection is facilitated by the interaction of RSV G with CX3CR1, which has been shown to depend upon the cystine noose." (PMID 29509814, 2018). "An “intermediate” CD14++CD16+ subpopulation and an activated (CD123+, CX3CR1+, and CD141+) CD14+ monocyte subpopulation associated most strongly with the acute phase of infection when compared against all other identified subpopulations of PBMCs." (PMID 30150281, 2018). "The cystine noose is thought to mediate RSV attachment to human airway epithelial cells during natural infection by interaction with CX3CR1." (PMID 29509814, 2018). "It has been demonstrated that RSV G protein CX3C motif reduced CX3CR1+ cell trafficking to the lungs during infection and eventually decreased antiviral response to RSV infection." (PMID 28076422, 2017). "We measured Ly6C and CCR2 expression on CD11b+CD24-CD64+CX3CR1+ putative monocytes on day 3 post-ch to determine the influence of infection and pre-existing immunity on monocyte maturation." (PMID 28666021, 2017). "We were able to define CD11b+CD24lowCD64+Ly6C+CCR2+CX3CR1+ inflammatory monocytes as the preferred mononuclear host cell for L. major following the initial neutrophil phase of infection." (PMID 28666021, 2017). "The G protein has been shown to bind to the fractalkine receptor, CX3CR1, and can use it to initiate infection when it is transiently expressed in immortalized cells." (PMID 26658574, 2015). "Perivascular CD8+ T cells were observed forming stable interactions with CX3CR1+/GFP cells, specifically during infection with ECM-causing Pb ANKA parasites." (PMID 26562533, 2015). "Experimental LCMV infection studies in mice revealed a high ratio of virus-specific CX3CR1+ to CX3CR1neg CD8+ T cells in resolved infection, whereas an inverted ratio was observed during chronic LCMV infection." (PMID 26404698, 2015). "Expression of CX3CR1 resulted in a 4-fold increase in infection as compared to the same cells transfected with empty vector." (PMID 26658574, 2015). "CX3CR1+ expression was observed after infection with adenovirus (AdOVA) or Listeria monocytogenes (L.m.-OVA) on OVA-specific memory CD8+ T cells and after LCMV infection on LCMV-gp33-specific memory CD8+ T cells." (PMID 26404698, 2015). "We next studied CX3CR1 expression on virus-specific CD8+ T cells during experimental infection with different LCMV clones in mice that is either resolved after acute infection (LCMV WE) or develops into chronic infection (LCMV clone 13)." (PMID 26404698, 2015). "Among CD44+ T cells, CX3CR1 expression was most prominent in CD8+ T cells, prompting us to study CX3CR1 expression on antigen-specific memory CD8+ T cells in response to infection." (PMID 26404698, 2015). "Among those, the frequency of GFP+ (CX3CR1+) CD8+ T cells was significantly increased in mice that successfully cleared acute LCMV WE infection compared with clone 13-infected mice." (PMID 26404698, 2015). "Infection caused CCR2-dependent increases in numbers of Ly6Chi monocytes in blood and liver and of CX3CR1+ macrophages in diseased liver." (PMID 25144366, 2014). "AAM recruited to liver granulomas following S. mansoni infection are CX3CR1-GFP+ using Cx3cr1gfp/+ reporter mice at seven weeks post-infection." (PMID 24967715, 2014). "By day 60 post-infection, the CX3CR1-GFP+/− microglia retained their enlarged, amoeboid morphology; however, vascular patrolling had declined to the levels observed in mock-infected control mice." (PMID 23737750, 2013).
infection (continued). "At day 15 post-infection, we observed a marked transformation in the morphology and dynamics of CX3CR1-GFP+/− cells (primarily microglia) in the brain parenchyma." (PMID 23737750, 2013). "CX3CR1 was shown to be downregulated in the early acute phase (22 h after infection) and upregulated in the late acute phase (44 h after infection) of BM." (PMID 21412436, 2011). "CX3CR1-signaling also has been shown to play a role in infections with other viruses." (PMID 40295855, 2024). "Unbiased t-distributed stochastic neighbor embedding (t-SNE) analysis combined with conventional gating of the myeloid cell population revealed that CX3CR1 was predominantly expressed in the F4/80+ macrophage and cDC2 populations during different stages of LucAdV5 infection." (PMID 39355243, 2024). "However, whereas γδ TCM remained mostly KLRG1-CX3CR1- in d92-infected mice, the proportion of KLRG1+CX3CR1+ cells among γδ TEM inflated upon infection." (PMID 38976755, 2024). "It is tempting to speculate that differentiated Th17 cells in secondary lymphoid organs could interact with CX3CR1+ macrophages within crypts during the late phase of infection." (PMID 39379604, 2024). "To investigate whether monocytes and neutrophils migrated to damaged foci during infection, we adoptively transferred BM cells from Cx3cr1‐Cre+ tdTomato reporter mice into WT and TMEM16F KO mice at 3 dpi." (PMID 39136057, 2024). "GITR was identified as a crucial enhancer of CX3CR1 expression on CD4+ T cells post-infection." (PMID 39061246, 2024). "However, the decline in the median during recovery for CD11cdimCD27+CD24−CD38hi B cells (B#18) (p = 7.1 × 10−3) and CD56dim CX3CR1+ NK cells (IL#10) (p = 3.0 × 10−3) and were statistically significant, implying that these subsets are infection-related." (PMID 38429462, 2024). "During intracellular infection, CX3CR1+ monocytes patrol through vessels in the epithelium." (PMID 37865711, 2023). "Thus, the RSV-G/CX3CR1 interaction is likely crucial in infection and infection-induced responses of the airway epithelium." (PMID 37764926, 2023). "Soluble G may thereby act as a chemoattractant resulting in the increased recruitment of CX3CR1+ immune cells to the site of infection." (PMID 37896776, 2023). "N178 G was located near the CX3C motif binding to CX3CR1 to initiate infection." (PMID 38235154, 2023). "Thus, a substantive fraction of memory CD8 T cells in circulation or in various tissues express CXCR3 and/or CX3CR1 and, hence, are poised to rapidly traffic into infected tissues such as lungs, upon infection." (PMID 37796612, 2023). "Furthermore, they reported that this was due to differential entry factor usage of RSV G protein between these cellular systems and the relevance of chemokine receptor CX3CR1 for infection of HAE cells." (PMID 36346232, 2022). "CX3CR1 had a higher expression level than the control group at the early stage of infection." (PMID 36169259, 2022). "For example, monocyte subset expression of CCR2 and CX3CR1 is altered in infection." (PMID 33717107, 2021). "Indeed, although markers such as PD-1 are strongly associated to LCMV clone 13 infection, KLRG1, CX3CR1, and NKG2A expression is mostly connected to MCMV, and Ly6Chi and CD127hi expression is connected to LCMV Armstrong." (PMID 33458613, 2021). "The murine infection model for the disease is characterized by CCL2/CCR2-dependent recruitment of Ly6Chi monocytes to the liver, and an increase in granuloma-associated resident CX3CR1+ macrophages." (PMID 33829283, 2021). "SARS‐CoV‐2 may primarily infect monocyte and CD14+ subsets with higher expressions of CCR2 and CX3CR1 which may differentiate and migrate from the periphery to the target sites as macrophages during infection." (PMID 34363351, 2021). "In addition, the viral chemokine vCXCL1, which is encoded by CMV, preferentially binds to CX3CR1 and CXCR1, and mediates the migration of CD56dim cells to the site of infection." (PMID 34452400, 2021).
infection (continued). "However, the number of interstitial macrophages in the lung after infection was significantly greater in the Ezh2fl/fl Cx3CR1‐cre mice." (PMID 34464475, 2021). "Further, CX3CR1 is a receptor used by RSV for infection of CRs." (PMID 34960746, 2021). "Moreover, one TEM cell cluster (Lu cluster 7) expressing Ly6C and CD127 was uniquely related to LCMV Armstrong, whereas upon MCMV-GP33 infection TEM cells with a KLRG1+CX3CR1+ phenotype were more abundant." (PMID 33458613, 2021). "This leads to inhibition of the influx of CX3CR1+ inflammatory cells to sites of infection." (PMID 33477301, 2021). "The high progesterone level might be the reason for the limited production of specific IgG and activation of CX3CR1+CD8+T cells in the pregnant mice after infection, which needed further experimental confirmation." (PMID 35126335, 2021). "Thus, this mutation, or other mutations that block binding to CX3CR1, has the potential to improve a live attenuated RSV vaccine by attenuating both infection and disease pathogenesis." (PMID 31330970, 2019). "Importantly, CX3CR1 is also an important receptor for infection of primary human airway epithelial cells (pHAECs) and blocking G binding to CX3CR1 decreases infection of pHAECs." (PMID 31330970, 2019). "Therefore, it has been proposed that RSV can bind different receptors in cells and in HAE, where CX3CR1 is sufficient for mediating the infection." (PMID 31266258, 2019). "There have been many discoveries about RSV-G in recent years, including its role in mediating attachment to CX3CR1 whereby the virus initiates infection of bronchial epithelial cells, as well as the putative role of secreted RSV-G in modulating the host immune response." (PMID 30717190, 2019). "Therefore, it is possible that CX3CR1 monocytes are recruited to the infection site, become infected, and differentiate into DCs." (PMID 30037007, 2018). "In our results, the association between lower CX3CR1 expression and fatal outcome was independent of the presence of either an infection or a shock." (PMID 27364780, 2016). "As our CX3CR1-/- mouse infection data suggest that RSV uses CX3CR1 as a receptor on the murine airway epithelium, RSV neutralization by mAb 131-2g could have directly caused the decrease in viral load, resulting in decreased pathogenesis." (PMID 26658574, 2015). "Upon infection, the distribution of CX3CR1 in these cells is significantly altered." (PMID 26107373, 2015). "Also in preclinical models of chronic viral infection, that is, lymphocytic choriomeningitis virus (LCMV) clone 13 infection, numbers of CX3CR1+ memory CD8+ T cells correlate with control of infection and response to immune therapy." (PMID 26404698, 2015). "Our team recently identified a novel subset of CD11b+F4/80hiCD64+CX3CR1+ MNPs that expand upon infection, secrete high levels of IL-10 and are required for maintaining elevated levels of H. pylori in the stomach mucosa early during infection." (PMID 26367386, 2015). "Interestingly, CX3CR1 is a requisite for rapid tissue invasion of resident monocytes at the site of infection in mice peritoneally infected with Listeria monocytogenes." (PMID 24631198, 2014). "Indeed the frequency of PD-L2 expressing CX3CR1-GFP+ cells in the liver peaks at 6 weeks post-infection, providing us with a surface marker to determine when CX3CR1-GFP+ cells begin to adopt the AAM phenotype." (PMID 24967715, 2014). "RSV G protein acts as a fractalkine receptor antagonist modulating the immune response to infection, and inhibiting fractalkine-mediated responses including altering pulmonary trafficking of CX3CR1+ immune cells, and modifying the magnitude and cadence of cytokine and chemokine expression." (PMID 24040360, 2013).
infection (continued). "Cell depletion experiments and infections in Cybb−/−Myd88−/− mice indicated that the S.Tmavir-inflicted disease in Cybb−/− mice hinges on CD11c+CX3CR1+ monocytic phagocytes mediating colonization of the cecal lamina propria and on Myd88-dependent proinflammatory immune responses." (PMID 24143212, 2013). "The infection had only a limited effect on the numbers of CD11c+ CX3CR1+ cells per villus." (PMID 24367259, 2013). "The observed down-regulation of chemokine (CCL4) and chemokine receptors (CCR1, CXCR2, CX3CR1, C5aR) could impair the proper inflammatory response at the site of infection as they play a crucial role in immune cell trafficking." (PMID 23626859, 2013). "Daily analysis during the course of infection revealed that CD11c+ CX3CR1+ macrophage-like cells continuously accumulated such that the count increased 3 fold between the first and second week of age, to reach a density close to that in 22-day-old and adult animals." (PMID 24367259, 2013). "However, how the gut microbiota regulates the expression of CX3CR1 on NK cells during infection remains unclear." (PMID 41532069, 2026). "Interestingly, while CX3CR1 serves as a marker for these highly differentiated CD4+ T cells, its absence or deficiency did not impact the accumulation of CD4+ T cells in key organs such as the spleen, lung, or liver during the infection." (PMID 39061246, 2024). "However, the direct interaction of G and CX3CR1 may not only affect the infection of AECs but also interfere with the CX3CR1-CX3CL1 interaction." (PMID 37896776, 2023). "In addition, the CX3C motif could induce migration of CX3CR1+ lymphocytes to the infection site via a chemo-trafficking mechanism in the airway and lung, which resulted in increased severity of inflammation during the RSV infection." (PMID 36535957, 2022). "In LCMV clone 13 infection, one TRM cell cluster expressing PD-1, CD38, CD39, CD54, and CXCR6 significantly associated with the liver, whereas a TEM cell subset of cells expressing high levels of PD-1, CX3CR1, NKG2A, and Ly6C (Cl13 cluster 5) was more abundant in the lungs and spleen." (PMID 33458613, 2021). "It is also worth noting that cell-associated viremia was only evident after i.p. infection in these experiments and that CX3CR1-knockout mice had elevated numbers of inflammatory monocytes at the site of infection, which may alter the local immune control and viral spread." (PMID 33508041, 2021). "Consequently to Jung work, Cx3cr1+/EGFP and Cx3cr1EGFP/EGFP mice have become widely used and EGFP fluorescence level was used to monitor CX3CR1 expression in several cell populations and its modulation through time and under several pathological conditions (e.g., inflammation, infection, cancer)." (PMID 32582197, 2020). "Additionally, expression of CX3CR1 by Ly6Chi monocytes in the blood was lower in gonadectomized and testosterone-supplemented male mice than in gonadectomized control mice on Day 3 p.i., reflecting the results obtained in male and female mice during infection." (PMID 32651360, 2020). "In addition, microglia related genes, and genes associated with microglial cell activation (Mki67, Cd40, Tmem119 and Cx3cr1) were significantly induced 4 days following VACV-Wyeth infection indicating the possible role of these cells in the induction of immune response in the brain." (PMID 30759813, 2019). "Thus, to more specifically identify and characterize the CX3CR1+/GFP cells present within the brain during the two infections, we isolated GFP+ leukocytes from the brains of infected and uninfected mice and characterized them for expression of phenotypic and functional markers." (PMID 26562533, 2015). "We hypothesized that the different nature of cognate interaction between T cells and CX3CR1+/GFP cells in the brains during Pb ANKA and Pb NK65 infections was due to alterations in the composition and/or activation of the brain CX3CR1+/GFP population during infection with Pb ANKA and Pb NK65." (PMID 26562533, 2015).